LOXL1 (lysyl oxidase like 1)
Diseases named in the same sentence as LOXL1 in open-access papers (continued):
Sharing a sentence is not in itself a finding about the gene and the disease.
breast carcinoma (14 papers, 2011 to 2025). "LOXL1 has also been implicated in fibrosis in response to inflammation in human breast cancer, in liver and lungs in model animals." (PMID 36797672, 2023). "Despite substantial evidence supporting the oncogenic role of LOXL1 in breast cancer, further basic experimental research is warranted to elucidate its precise molecular mechanisms." (PMID 39247609, 2024). "According to the analysis of the Cancer Genome Atlas (TCGA) database, LOXL1 is expressed at elevated levels in breast cancer (p< 0.05), whereas LOXL4 is expressed at low levels (p < 0.05)." (PMID 39247609, 2024). "In that sense, LOX and LOXL1-4 are interesting candidates as novel targets to modulate breast cancer progression." (PMID 35800439, 2022). "Lysyl oxidase (Loxl1), a matrix remodeling protein, is known to play a role in breast cancer migration, adhesion, and metastasis." (PMID 21589862, 2011). "We co-treated breast cancer cells MDA-MB-231 (with high LOXL1 and BAG2 expression) with HSP90 inhibitor (IPI-504), HSP70 inhibitor (VER-155008), LOX inhibitor (BAPN), or NAMPT (FK886) inhibitor and doxorubicin, and we observed the survival rate to calculate the drug interactions." (PMID 40426862, 2025). "As a result, LOXL1 is highly expressed in breast cancer and has carcinogenic effects." (PMID 39247609, 2024). "In our analysis, further clarity is needed to verify whether LOXL1 is a friend or foe in breast cancer." (PMID 37056938, 2023). "Consequently, LOX and LOXL1–4 enzymes have been suggested as potential druggable targets to prevent breast cancer metastasis." (PMID 35800439, 2022). "Additionally, LOXL1 knockdown disrupts ECM remodelling in ILC tumours, attenuats ER signal transduction, and affects tumour growth, invasion, and metastasis in vivo, and it is linked to increased malignancy in breast cancer." (PMID 39247609, 2024). "Knockdown of LOXL1 in MDA-MB-231 and MCF7 breast cancer cells results in a significant decrease in cell proliferation and migration." (PMID 39247609, 2024). "In this study, BM genes with differential expression and prognostic correlation in breast cancer were selected as promising prognostic biomarkers for breast cancer, including FBLN1, FBLN5, ADAMTS8, LOXL1, SDC1 and PXDNL." (PMID 37056938, 2023). "Based on the TCGA-BRCA dataset, we found that LOXL1, SDC1 and PXDNL were highly expressed in breast cancer while the expressions levels of FBLN1, FBLN5 and ADAMTS8 were lower than those in normal breast samples." (PMID 37056938, 2023). "Next, we analyzed the breast cancer patient data for correlation between OSMR mRNA expression and other lysyl oxidase family members: LOX and LOXL1-4." (PMID 34011405, 2021). "Similarly, LOXL1 promotes angiogenesis and EMT in GBM, osteosarcoma, prostate cancer, colon cancer, and breast cancer, making it a key driver of tumor dissemination and metastasis." (PMID 41498024, 2025). "Therefore, breast cancer cells with relatively low expression of BAG2 and LOXL1 may have a high possibility of resistance to IPI-504." (PMID 40426862, 2025). "We speculate that while the impact of LOXL3 inhibition may vary with breast cancer subtype, the therapeutical inhibition of LOX, LOXL1 and LOXL2 but not of LOXL4 may be the most beneficial." (PMID 35800439, 2022). "Overall, we speculate that while the impact of LOXL3 inhibition may vary with breast cancer subtype, the specific therapeutical inhibition of both LOXL1 and LOXL2 but not of LOXL4 may be beneficial in breast cancer." (PMID 35800439, 2022).
gastric cancer (10 papers, 2020 to 2025). A primary or metastatic malignant neoplasm involving the stomach. "Regarding LOXL1 in gastric cancer, one study indicates that LOXL1 has been associated with peritoneal dissemination, which frequently occurs in gastric cancer." (PMID 40906383, 2025). "LOXL1 overexpression reduced CDH1 expression and promoted the migration capacity of gastric carcinoma cells and associates LOXL1 with peritoneal dissemination in gastric cancer possibly via promotion of EMT." (PMID 33616307, 2021). "Interestingly, LOXL1 expression has been associated with gastric cancer with intestinal-type histology." (PMID 40906383, 2025). "The expression of LOXL1 was correlated with T invasion, lymph node metastasis, and lymphatic and venous invasion in gastric cancer samples." (PMID 40906383, 2025). "High levels of LOX like 1 (LOX-1) expression in gastric cancer by epithelial-mesenchymal transition (EMT) and LOXL-1,-3 and LOXL -4 association in gastric cancer was reported in a previous study." (PMID 35054220, 2021). "In addition, the expression of LOXL1 was found to be correlated with T invasion, lymph node metastasis, and lymphatic and venous invasion in gastric cancer." (PMID 33790946, 2021). "In gastric cancer (GC), upregulation of LOXL1 correlates with poorer differentiation, lymph node metastasis, and unfavorable prognosis." (PMID 38267662, 2024). "Several studies have reported changes in LOX, LOXL1, LOXL2, LOXL3, and LOXL4 expression in gastric cancer." (PMID 40906383, 2025). "Studies have reported that the expression of LOX family members LOXL1, LOXL3, and LOXL4 is related to distant metastasis of gastric cancer." (PMID 34595188, 2021). "Interestingly, LOXL1 downregulates CDH1 and upregulates VIM, CDH2, PLS3, and SNAI2 in gastric cancer cells, where expression of LOXL1 correlates with EMT." (PMID 34023917, 2021).
liver fibrosis (9 papers, 2016 to 2024). "LOX secreted by HCC promotes tube formation of endothelial cells through upregulation of VEGF, and overexpressed LOX increases angiogenesis, whereas LOXL1 was found to be increased in liver fibrosis models." (PMID 35311155, 2022). "Meanwhile, the phosphorylation of Smad2/3 also encourages the acceleration of MMP1, α-SMA, and collagen type I, which results in the overexpression of lysyl oxidase-like 1 (LOXL1) to promote liver fibrosis." (PMID 35461253, 2022). "The knockdown of LOXL1 led to mitigation of liver fibrosis in vivo and decreases in fibrogenic markers in the hepatic stellate cell (HSC) line LX-2 in vitro." (PMID 33371259, 2020). "Therefore, upregulation of LOXL1 gene expression will promote the development of liver fibrosis and even cirrhosis." (PMID 37808522, 2023). "A previous study found a 30-fold increase of LOXL1 level in a liver fibrosis model." (PMID 35311155, 2022). "LOX proteins (LOX, LOXL1, LOXL2, LOXL3, and LOXL4) are extracellular copper‐dependent enzymes and have been identified as potential therapeutic targets in liver fibrosis." (PMID 38853023, 2024). "For example, downregulation of the LOXL1 enzyme led to reduction of collagen and elastin expression alongside decreased elastin cross-linking in the murine CCL4 model of liver fibrosis." (PMID 33498156, 2021). "A difference in LOXL1 gene expression between groups did not translate to a difference in protein concentration, and therefore it is less likely that LOXL1 is a significant mediator of the hepatocyte HIF-1 effect on liver fibrosis." (PMID 28030556, 2016).
pulmonary fibrosis (7 papers, 2018 to 2025). Chronic progressive interstitial lung disorder characterized by the replacement of the lung tissue by connective tissue, leading to progressive dyspnea, respiratory failure, or right heart failure. "In animal models of hepatic and pulmonary fibrosis, LOXL1 has been shown to regulate TGFB-induced fibrosis, and its knockdown inhibits fibrotic proliferation and reduces expression of type I collagens and pro-fibrotic metalloproteinases." (PMID 41026521, 2025). "Among the top differentially expressed genes we found SPARC, LOXL1, and APP which have been implicated in lung fibrosis." (PMID 37085855, 2023). "Increased expression of LOXL1 is observed in fibrotic diseases such as idiopathic pulmonary fibrosis, while decreased expression is reported in XFS." (PMID 34440405, 2021). "In other disease models including idiopathic pulmonary fibrosis and liver cirrhosis, LOXL1 was shown to be stimulated by pro-fibrotic TGFB to increase cross-linking, and its knockdown protects from fibrosis and reduces expression of pro-fibrotic metalloproteases and collagens." (PMID 41026521, 2025). "Taken together, the elevated levels of POSTN, THBS2, COL6A1, and LOXL1 may contribute to the development of pulmonary fibrosis, similar to what is seen in IPF, thus connecting fibrosis to inflammation in DM-ILD." (PMID 37928522, 2023).
bladder cancer (6 papers, 2018 to 2025). "LOXL1/4 gene methylation and loss of expression is commonly observed in primary bladder cancer cells, and LOXL1/4 reintroduction into these cells can reduce colony formation." (PMID 29732010, 2018). "Wu et al42 reported that LOXL1 exerted an antitumor function in human bladder carcinoma by antagonizing the Ras/ERK signaling pathway." (PMID 33058284, 2020). "Research has indicated that the LOXL1 protein is reduced in human renal cell carcinoma (RCC) and bladder cancer (BLCA), where it acts to suppress tumor growth." (PMID 40786111, 2025). "LOX and LOXL2 reportedly promote kidney carcinoma tumorigenesis, while LOX, LOXL1 and LOXL4 suppress bladder cancer growth." (PMID 29732010, 2018).
cardiac hypertrophy (5 papers, 2019 to 2023). "In turn, transgenic mice with cardiomyocyte-specific expression of LOXL1 developed cardiac hypertrophy." (PMID 31766500, 2019). "In addition, stimulation with hypertrophic agonists increased LOXL1 expression in rat cardiomyocytes in vitro and cardiac hypertrophy with fibrosis in vivo which was abrogated by adding a the LOXL1 inhibitor." (PMID 37443910, 2023). "Similarly, Ang II-induced cardiac hypertrophy was exacerbated in transgenic mice that overexpress LOXL1 specifically in cardiomyocytes, which exhibited myocyte hypertrophy, and higher mRNA levels of brain natriuretic peptide (Bnp) than their WT littermates." (PMID 31766500, 2019). "Thus, LOXL1 also seems to critically contribute to cardiac hypertrophy." (PMID 31766500, 2019). "Transgenic overexpression of LOX or LOXL1 aggravated cardiac hypertrophy in mice with or without angiotensin II induction." (PMID 36159334, 2022).
colorectal cancer (5 papers, 2020 to 2025). A primary or metastatic malignant neoplasm that affects the colon or rectum. "Analysis of data from multiple databases, including UALCAN, TIMER 2.0, and TNMplot, consistently indicates an upregulation of LOXL1 expression in colorectal cancer compared to normal tissue." (PMID 38267662, 2024). "LOXL1 expression in colorectal cancer was detected by immunohistochemistry, western blotting and real-time PCR." (PMID 32912229, 2020). "The expression of LOXL1 in colorectal cancer (CRC) remains a topic of debate, as it may either be upregulated or downregulated." (PMID 40786111, 2025).
glioblastoma (5 papers, 2022 to 2025). The most malignant astrocytic tumor (WHO grade IV). "We found that TIMP1, ITGA5, FCGR2B, UPP1, ISG20, TSPAN4, and LOXL1 are potential biomarkers correlated with the immune infiltration events in patients with glioblastoma." (PMID 35778451, 2022). "Through analyzing patients’ clinical information and genetic profiles from online databases, TIMP1, ITGA5, FCGR2B, UPP1, ISG20, TSPAN4, and LOXL1 were identified as potential prognostic biomarkers for glioblastoma." (PMID 35778451, 2022). "In addition, we used the SurvExpress analysis to further assess the prognostic value of TIMP1, ITGA5, FCGR2B, UPP1, ISG20, TSPAN4, and LOXL1 using other glioblastoma patient cohorts, including TCGA Glioblastoma and GSE4412." (PMID 35778451, 2022). "To investigate the impact of the LOX family on glioblastoma, we analyzed the expression of LOX family members (LOX, LOXL1, LOXL2, LOXL3, and LOXL4) in normal human astrocytes (Heb) and glioblastoma cell lines (T98G and LN-229)." (PMID 40270974, 2025). "LOXL1 correlations were detected in LGG with IDH mutation (IDHmut), LOXL3 correlations in LGG with IDH wild type (IDHwt) and strong LOX correlations in glioblastoma (GBM) were found." (PMID 36076905, 2022).
non-small cell lung carcinoma (5 papers, 2019 to 2025). A group of at least three distinct histological types of lung cancer, including non-small cell squamous cell carcinoma, adenocarcinoma, and large cell carcinoma. "LOXL1 expression is associated with chemotherapy resistance in pancreatic ductal carcinoma and non-small cell lung cancer (NSCLC)." (PMID 32912229, 2020). "Secondly, overexpression of lysyl oxidase-like 1 (LOXL-1) in a non-small cell lung cancer metastasis model was associated with the upregulation of MCT1/2, increased expression and activity of MMP2/9, and increased cell migration and invasion, along with increased extracellular lactate at a low pH." (PMID 35267606, 2022). "It is known that LOXL1 is expressed in stromal cells and promotes non-small cell lung cancer tumorigenesis by extracellular matrix remodeling." (PMID 33095806, 2020).
lung cancer (4 papers, 2019 to 2022). A malignant neoplasm involving the lung. "LOXL1 overexpression enhances the invasiveness of lung cancer cells, and tumor cells with high LOXL1 expression yielding more cancer nodules through injection into mouse tail veins." (PMID 36293126, 2022). "In non‐small cell lung cancer (NSCLC), cancer‐associated fibroblast (CAF)‐secreted LOXL1 provides a microenvironment that facilitates tumor growth and invasion by affecting collagen fiber remodeling." (PMID 35152572, 2022). "However, Lee et al41 provided evidence that LOXL1 was overexpressed in metastatic sites compared to primary lung cancer tissues and that the upregulation of LOXL1 promoted lung cancer cell metastasis and invasiveness when extracellular lactate accumulated, suggesting that LOXL1 was an oncogene." (PMID 33058284, 2020).
osteosarcoma (4 papers, 2024 to 2026). A usually aggressive malignant bone-forming mesenchymal neoplasm, predominantly affecting adolescents and young adults. "Analysis of the GEO database revealed that LOXL1, LOXL2, and LOXL3 expression levels were significantly elevated in osteosarcoma tissue samples compared to normal bone, indicating their involvement in disease progression." (PMID 41399365, 2026). "In vitro experiments confirmed that treatment of osteosarcoma cells with FGF-23 increased LOXL2 mRNA and protein expression in a dose-dependent manner, while the effects on LOXL1 and LOXL3 were comparatively limited." (PMID 41399365, 2026). "Gene Expression Omnibus (GEO) analysis indicated that lysyl oxidase-like proteins—particularly LOXL1, LOXL2, and LOXL3—are overexpressed in osteosarcoma tissues compared to adjacent normal bone." (PMID 41399365, 2026). "To further verify the expression of LOXL1 in rheumatoid arthritis synovium, we used TNF-α to stimulate human osteosarcoma synovial cells for 48 h, extracted total protein and total mRNA, and detected the expression of LOXL1, INOS, COX2, and IL-6 in them through RT-qPCR and western blot." (PMID 38217541, 2024).
pigment dispersion syndrome (4 papers, 2008 to 2024). Pigment-dispersion syndrome is an eye disorder that occurs when pigment granules that normally adhere to the back of the iris (the colored part of the eye) flake off into the clear fluid produced by the eye (aqueous humor). "The aim of our study is to investigate a potential involvement of LOXL1 gene in the pathogenesis of pigment dispersion syndrome (PDS) and pigmentary glaucoma (PG)." (PMID 24739284, 2014). "To further establish the specificity of LOXL1 SNPs for XFS and XFG, we determined whether these SNPs were involved in pigment dispersion syndrome (PDS) and pigmentary glaucoma (PG)." (PMID 18618003, 2008).
atherosclerosis (3 papers, 2017 to 2025). A disease characterized by the build-up of fatty material and calcium deposition in the arterial wall resulting in partial or complete occlusion of the arterial lumen. "The abnormal expression or activation of LOXL1 can disrupt the cellular microenvironment, contributing to the development of various diseases, such as atherosclerosis, tissue damage, fibrosis, and cancer." (PMID 40786111, 2025). "Given that EMILIN1 and LOXL1 are involved in the regulation of vascular assembly and flexibility, it is possible that deamidation leading to functional impairment of these proteins could promote atherosclerosis in human patients." (PMID 28720870, 2017).
idiopathic pulmonary fibrosis (3 papers, 2020 to 2025). Idiopathic pulmonary fibrosis (IPF) is a nonneoplastic pulmonary disease that is characterized by the formation of scar tissue within the lungs in the absence of any known cause. "Collagen crosslinking mediated by the lysyl oxidase family of enzymes (LOX, LOXL1-4) contributes to the pathogenesis of idiopathic pulmonary fibrosis (IPF), a progressive scarring lung disease which predisposes patients to lung cancer, mostly NSCLC." (PMID 33114183, 2020).
intrahepatic cholangiocarcinoma (3 papers, 2022 to 2025). A carcinoma that arises from the intrahepatic bile duct epithelium in any site of the intrahepatic biliary tree. "LOXL1 highly expressed in intrahepatic cholangiocarcinoma (ICC) can interact with FBLN5, an extracellular matrix glycoprotein containing the Arg-Gly-Asp (RGD) structural domain." (PMID 36293126, 2022). "In intrahepatic cholangiocarcinoma (ICC), elevated LOXL1 expression interacts with fibulin-5 (FBLN5), an extracellular matrix glycoprotein containing the Arg-Gly-Asp (RGD) motif." (PMID 40786111, 2025). "In addition, it was confirmed that LOXL1, the protein interacting with FBLN5, stimulated angiogenesis through the LOXL1-FBLN5/avb3 integrin/FAK-MAPK axis in intrahepatic cholangiocarcinoma, which resulted in favorable conditions for cancer cell metastasis." (PMID 36672502, 2023).
liver cancer (3 papers, 2020 to 2024). An epithelial or non-epithelial malignant neoplasm that arises from the liver. "In liver cancer cells treated with 5 and 20 mM glucose, the inhibition of LOXL1 AS1 resulted in a significant reduction in glucose uptake." (PMID 38184562, 2024). "Considering the role of LOXL1 in cancer progression, it would be an interesting topic to investigate the role of LOXL1 in liver cancer and the possibility of NK cells’ therapeutic effects." (PMID 37189708, 2023). "Several lines of study have highlighted the role of LOXL1 in tumor progression, such as glioma, gastric cancer, colorectal cancer, pancreatic ductal adenocarcinoma (PDAC), yet its effect on liver cancer remains unclear." (PMID 33371259, 2020).
liver cirrhosis (3 papers, 2023 to 2025). "LOXL1, a member of the lysyl oxidase (LOX) family of enzymes involved in collagen and elastin crosslinking, has also been linked to liver cirrhosis." (PMID 38565287, 2024). "In addition, we reported that lysyl oxidase-like-1 (LOXL1) was related to NK cell therapeutics in the CCl4-induced liver cirrhosis mouse model." (PMID 37189708, 2023).